SRP72 (signal recognition particle 72)
Description:
Component of the signal recognition particle (SRP) complex, a ribonucleoprotein complex that mediates the cotranslational targeting of secretory and membrane proteins to the endoplasmic reticulum (ER). The SRP complex interacts with the signal sequence in nascent secretory and membrane proteins and directs them to the membrane of the ER. The SRP complex targets the ribosome-nascent chain complex to the SRP receptor (SR), which is anchored in the ER, where SR compaction and GTPase rearrangement drive cotranslational protein translocation into the ER. Binds the signal recognition particle RNA (7SL RNA) in presence of SRP68. Can bind 7SL RNA with low affinity. The SRP complex possibly participates in the elongation arrest function (By similarity).
Synonyms: BMFF; BMFS1; HEL103
Tractability: Small molecule: a structure with a bound ligand is known. PROTAC: UniProt records ubiquitination sites on it; ubiquitination databases record sites on it; its protein half-life has been measured.
Gene: Protein-coding gene on chromosome 4 (56,467,595 to 56,503,681, forward strand). Ensembl gene ENSG00000174780.
Subcellular location: Cytoplasm; Endoplasmic reticulum
Pathways (Reactome):
Metabolism of proteins: SRP-dependent cotranslational protein targeting to membrane
Gene Ontology:
Molecular function: 7S RNA binding; protein binding; ribosome binding; RNA binding; signal recognition particle binding; TPR domain binding
Biological process: SRP-dependent cotranslational protein targeting to membrane; SRP-dependent cotranslational protein targeting to membrane, signal sequence recognition
Cellular component: cytoplasm; endoplasmic reticulum; signal recognition particle; signal recognition particle, endoplasmic reticulum targeting; cytosol
Genetic constraint (gnomAD): Loss-of-function variants: 36 observed, 81.93 expected, observed/expected ratio (o/e) 0.44, 90% interval 0.34 to 0.58. The upper end of that interval is the gene's LOEUF score, 0.58, which puts it in group 2 of 6, group 1 being the genes least tolerant of losing a copy. Missense variants: 645 observed, 718.75 expected, observed/expected ratio (o/e) 0.9, 90% interval 0.84 to 0.96. Synonymous variants: 241 observed, 252.43 expected, observed/expected ratio (o/e) 0.95, 90% interval 0.86 to 1.06.
Homologues: Orthologues: macaque SRP72 (99% identical), dog SRP72 (99% identical), guinea pig SRP72 (98% identical), rabbit SRP72 (98% identical), rat Srp72 (97% identical), mouse Srp72 (96% identical), chimpanzee SRP72 (96% identical), pig SRP72 (94% identical), rat AABR07002546.1 (92% identical), tropical clawed frog srp72 (79% identical), zebrafish srp72 (68% identical), Drosophila melanogaster Srp72 (40% identical), and 1 more.
Diseases named in the same sentence as SRP72 in open-access papers:
SRP72 is named in the same sentence as 35 diseases in open-access papers, as found by Europe PMC text mining. Sharing a sentence is not in itself a finding about the gene and the disease. The quoted sentences say what the papers report.
bone marrow failure (6 papers, 2016 to 2026). "The patient we reported is the seventh case of bone marrow failure caused by an SRP72 gene mutation worldwide and the first case in China." (PMID 41472573, 2026). "To broaden the molecular and clinical understanding of BMFS1, we report the phenotype of a 6‐year‐old boy with a novel splicing pathogenic variant in the SRP72 gene, identified using a panel sequencing associated with bone marrow failure." (PMID 41472573, 2026). "Germline SRP72 mutations have been identified in patients with inherited bone marrow failure and AML, but how these mutations affect SRP functions remains incompletely understood." (PMID 37002311, 2023). "In addition, one of 96 patients with bone marrow failure was found to have an SRP72 gene mutation (c.620G>A, p.Arg207His), which was inherited from her mother, who also had bone marrow failure." (PMID 41472573, 2026). "The findings provide new insights into the molecular mechanisms of BMFS1 and underscore the role of SRP72 in bone marrow failure." (PMID 41472573, 2026). "Autosomal-dominant mutations in SRP72 were identified in the pathophysiology of aplastic anemia (AA) and myelodysplasia (MDS), two forms of bone marrow failure that are associated with an increased risk of hematologic malignancy." (PMID 34113652, 2021). "SRP72, SRP54 and SRP68 display mutations associated with bone marrow failure, opening a new window into the pathophysiology of SRP and genetic diseases." (PMID 34113652, 2021). "Germline mutations in the ribonucleoprotein complex gene SRP72 (Signal Recognition Particle 72 kDa) have been identified as a rare cause of familial MDS and bone marrow failure." (PMID 27248996, 2016). "SRP72 has been identified in two families with bone marrow failure and myeloid dysplasia." (PMID 39501104, 2025).
aplastic anemia (4 papers, 2024 to 2026). Anemia resulting from bone marrow failure (aplastic or hypoplastic bone marrow). "According to the reported families, common manifestations of BMFS1 with SRP72 gene mutations include aplastic anemia, pancytopenia, myelodysplasia." (PMID 41472573, 2026). "It is known that polymorphisms in SRP72 are associated with one of the hereditary forms of aplastic anemia." (PMID 39409743, 2024). "We reported a 6‐year‐old boy with aplastic anemia and pancytopenia, where panel sequencing revealed a de novo splicing variant, c.1502+1G>A, in SRP72, causing BMFS1." (PMID 41472573, 2026).
Pancytopenia (3 papers, 2025 to 2026). An abnormal reduction in numbers of all blood cell types (red blood cells, white blood cells, and platelets). "Here, we report a novel frameshift mutation in the SRP72 gene identified in a 14-year-old patient presenting with pancytopenia." (PMID 40922878, 2025). "Here, we report a novel variant in the SRP72 gene identified in a 14-year-old patient presenting with pancytopenia." (PMID 40922878, 2025). "Our patient represents the third reported case, to the best of our knowledge, of pancytopenia associated with an SRP72 mutation but without accompanying deafness or a family history of disease." (PMID 40922878, 2025).
bone marrow failure syndrome 1 (2 papers, 2025 to 2026). "This study reports a rare case of bone marrow failure syndrome type 1 (BMFS1) caused by a novel de novo splicing mutation (c.1502+1G>A) in the SRP72 gene." (PMID 41472573, 2026).
autoimmune disease (1 paper, 2021). A disorder resulting from loss of function or tissue destruction of an organ or multiple organs, arising from humoral or cellular immune responses of the individual to their own tissue constituents. "Using sera from patients with different autoimmune diseases, SRP72 was the only SRP component identified to be phosphorylated and cleaved during apoptosis." (PMID 34113652, 2021). "Targeting SRP72 post-translational modification could be used for the treatment of patients with autoimmune diseases and/or to prevent some envelop virus replication." (PMID 34113652, 2021).
bladder carcinoma (1 paper, 2017). "The T24 (bladder carcinoma), PSN-1 (pancreatic adenocarcinoma), MCF7 and BT-549 (2 breast ductal carcinoma) cell lines were all radiosensitized following depletion of SRP72 using siSRP72–1." (PMID 28494188, 2017).
blood disease (1 paper, 2026). A disease that occurs in the blood. "The proband, who carried an SRP72 gene deletion (chr4.57340035_57349299del), had neonatal transfusion dependence with malformation syndrome, and her sister died of an undiagnosed blood disease at the age of 8 months." (PMID 41472573, 2026).
breast carcinoma (1 paper, 2024). "We constructed a risk model based on the expression levels of these RBPs and found that ADAT2, C2orf15, SRP72, PAICS, RBMS3, APOBEC3G, NOA1, and ACO1 could be used for risk assessment in terms of breast cancer prognosis." (PMID 38783078, 2024). "RBM47, PCBP3, FRG1, SRP72 and other RBPs might regulate AS of ITGA6, ADGRE5, TNC and other genes and affect the EMT process of breast cancer cells." (PMID 38783078, 2024). "It was found in our study that RBM47, PCBP3, FRG1, SRP72 and other RBPs may regulate the AS of ITGA6, ADGRE5, TNC and other genes and affect the EMT process of breast cancer cells." (PMID 38783078, 2024). "By further analysing above EMT-related RBPs and AS in breast cancer tissues in TCGA, it was found that the expression levels of ADAT2, C2orf15, SRP72, PAICS, RBMS3, APOBEC3G, NOA1, ACO1 and the AS of TNC and COL6A3 were significantly correlated with the prognosis of breast cancer patients." (PMID 38783078, 2024). "By establishing the correlation network of differential RBPs and differential AS events, we found that RBM47, PCBP3, FRG1, SRP72, RBMS3 and other RBPs may regulate the AS of ITGA6, ADGRE5, TNC, COL6A3 and other cell adhesion genes, which may affect the EMT process of breast cancer cells." (PMID 38783078, 2024).
head and neck cancer (1 paper, 2017). A primary or metastatic malignant neoplasm affecting the head and neck. "In one cell line, the head and neck cancer line, SQ20B, depletion of SRP72 was completely lethal, suggesting that the degree of SRP72 dependency is cell line specific." (PMID 28494188, 2017).
head and neck squamous cell carcinoma (1 paper, 2017). A squamous cell carcinoma that arises from any of the following anatomic sites: lip and oral cavity, nasal cavity, paranasal sinuses, pharynx, larynx, and salivary glands. "In the head and neck squamous cell carcinoma cell line SQ20B, SRP72 knockdown was completely lethal (Plating efficiency was 0% for SRP72 siRNA versus 31% for siNT)." (PMID 28494188, 2017).
neutropenia (1 paper, 2025). A decrease in the number of neutrophils found in the blood. "Of these, seven patients also had genetically determined neutropenia: five of them had defects of the ELANE gene, and the next two had changes in SRP72 (Pro257Arg) and TCIRG (Ala417Thr) genes." (PMID 41383606, 2025). "CLPB-related neutropenia also accounted for 10% of cases, followed by defects in the TCIRG1 (eight cases), CXCR4 (seven cases), and SRP72 genes (seven cases)." (PMID 41383606, 2025).
pancreatic cancer (1 paper, 2022). "The study of pancreatic cancer PSN-1 cells indicated that the knockdown of SRP72 resulted in a significant increase in sensitization to radiation therapy as measured by colony formation assays, indicating that SRP72 is a marker of radiotherapy resistance against cancer." (PMID 36338771, 2022).
thyroid cancer (1 paper, 2021). "A deletion in Srp72 gene (4q22.3) was also implicated in copy number variation in thyroid cancer, suggesting that this gene may contribute to the formation and progression of thyroid cancer in various ways." (PMID 34113652, 2021). "Srp72 gene was a recurrent mutated cancer-driving gene in thyroid cancer." (PMID 34113652, 2021). "Srp72 is overexpressed and hypomethylated which suggests it may have oncogenic function in thyroid cancer by altering the methylation status." (PMID 34113652, 2021).
cancer (4 papers, 2017 to 2025). A tumor composed of atypical neoplastic, often pleomorphic cells that invade other tissues. "In prostate cancer, Srp72 gene was identified as a downstream target of the cancer biomarker TWIST, associated with cancer invasion and metastasis." (PMID 34113652, 2021). "The discovery of the primary hydrophobic, concave bonding region on SRP72 linked to SRP68 opens doors for the creation of compounds that could be utilized in treating cancer." (PMID 40042106, 2025). "There is minimal literature regarding SRP72 and its involvement in cancer progression or radioresistance." (PMID 28494188, 2017). "However, the normal lung fibroblast cell lines, MRC-5 and HFL1 were both significantly radiosensitized following the knockdown of SRP72, suggesting that targeting SRP72 in cancer patients is unlikely to improve the therapeutic window." (PMID 28494188, 2017).
hematological disorder (3 papers, 2023 to 2026). "Our case expands the mutation spectrum of the SRP72 gene and highlights the importance of genetic testing in identifying hematologic disorders." (PMID 40922878, 2025). "Mice with heterozygous loss of SRP72 showed mild reductions in blood and bone marrow cellularity and minor changes within the stem/progenitor compartment, but no hematological disorder was observed." (PMID 41472573, 2026). "No family history of hematological malignancies was noted for the two cases carrying the SRP72 and DDX41 variants." (PMID 37002311, 2023). "However, the half-sister of the SRP72-mutated patient was diagnosed with certain non-malignant hematological disorders at a teenage requiring long-term use of medications." (PMID 37002311, 2023).
tumor (2 papers, 2017 to 2023). "Depletion of SRP72 caused radiosensitization in tumor lines derived from several histological sites suggesting that it is not restricted to tumor type." (PMID 28494188, 2017). "This differential expression between tumor and normal tissues raised the possibility that disruption of SRP72 might cause tumor specific effects and therefore be an effective therapeutic strategy." (PMID 28494188, 2017). "The aim of this study is to validate SRP72 as a modulator of tumor radiosensitivity." (PMID 28494188, 2017). "To gauge whether SRP72 could be a potential therapeutic target, we sought to determine whether the radiosensitization was tumor specific." (PMID 28494188, 2017). "SRP72 was chosen for further investigation because it had not been previously associated with radiosensitivity and Oncomine data suggested an elevated expression in tumor samples." (PMID 28494188, 2017). "Knockdown of SRP72 resulted in significant radiosensitization of HeLa (cervical), PSN-1 (pancreatic), and T24 (bladder), BT-549 (breast) and MCF7 (breast) tumor lines as measured by colony formation assays." (PMID 28494188, 2017). "SRP72 is the least characterized subunit of the SRP ribonucleoprotein complex, and its role in tumor radioresistance is unknown." (PMID 28494188, 2017). "SRP72 depletion also resulted in the radiosensitization of normal lung fibroblast cell lines (HFL1 and MRC-5), demonstrating that the effect is not restricted to tumor cells." (PMID 28494188, 2017).
SRP72 also shares sentences with these, for which no sentence is quoted: bone marrow failure syndrome (3 papers); Myelodysplasia (2); Myelodysplastic Neoplasm (2); acute myeloid leukemia (1); AMeD syndrome (1); breast ductal carcinoma (1); deafness (1); dwarfism (1); Immunodeficiency (1); Intellectual disability (1); LIG4 syndrome (1); malformation syndrome (1); melanoma (1); myeloid neoplasm (1); Noonan-like syndrome (1); Onset (1); pancreatic adenocarcinoma (1); Rothmund-Thomson syndrome (1); Thrombocytopenia (1).